VCAM1 (vascular cell adhesion molecule 1)
Diseases named in the same sentence as VCAM1 in open-access papers (continued):
Sharing a sentence is not in itself a finding about the gene and the disease.
atherosclerosis (continued). "Soluble VCAM-1 has been found to contribute to the attachment of inflammatory cells to the vascular endothelial wall, as well as the promotion of their subsequent migration through the endothelium, accelerating atherosclerosis." (PMID 36555301, 2022). "Similarly, S1P by activating S1PR3 can also promote the development of atherosclerosis, as does S1PR1 by activating endothelial ICAM-1 and VCAM-1 and causing its dysfunction." (PMID 36119733, 2022). "Moreover, activation of VCAM-1-VLA-4 signaling is associated with several types of CVDs, such as hypertensive and ischemic diseases, atherosclerosis, stroke, heart failure (HF), arrhythmias and AF." (PMID 36467095, 2022). "The increased IL-4 level might also aggravate the progression of atherosclerosis through its role in monocyte recruitment via the upregulation of VCAM-1 in ECs." (PMID 36497143, 2022). "However, in atherosclerosis, as well as in TNFα-induced brain injury in murine models, the importance of Vcam-1 activation was much more substantial than that of Icam-1." (PMID 35177109, 2022). "Molecules such as E-selectin and P-selectin, vascular cell adhesion molecule-1 (VCAM-1), and intercellular adhesion molecule-1 (ICAM-1) are predictors of endothelial dysfunction, representing an early marker of atherosclerosis events associated with cardiovascular risk factors." (PMID 36555645, 2022). "Investigations of IL-33 in atherosclerosis revealed that this cytokine stimulates the expression of the endothelial adhesion molecules VCAM1, ICAM1 and E-selectin as well as the expression of CCL2 in HUVECs in a concentration-dependent manner resulting in increased leukocyte adhesion." (PMID 35600479, 2022). "The lowering of VCAM-1 levels may indicate reduced atherosclerosis, as the level of circulating cell adhesion molecules is positively correlated with the degree of atherosclerosis in humans." (PMID 35224058, 2022). "Senescent ECs may promote monocyte recruitment to vascular endothelium via increased MCP-1, ICAM-1, or VCAM-1 in the early stage of atherosclerosis and may increase thrombosis via activated PAI-1." (PMID 36232471, 2022). "In particular, the relevance of the overexpression of endothelial adhesion proteins in the early stages of atherosclerosis development was firstly demonstrated by the observation that cholesterol accumulation in the vasal intima induced the increased expression of VCAM-1 on endotheliocyte membranes." (PMID 34371717, 2021). "Furthermore, oleuropein also protects atherosclerosis by reducing monocytoid cell adhesion to stimulated endothelium and vascular cell adhesion molecule-1 (VCAM-1) mRNA protein, which was essential in the early steps of atherogenesis." (PMID 33868820, 2021). "VCAM-1 has attracted a great deal of interest as a potential target for inflammation detection and, consequently, for atherosclerosis diagnosis, because it is scarcely expressed by healthy endothelium, while being rapidly upregulated in damaged and lesion-predisposed vascular regions." (PMID 34371717, 2021). "This study investigated whether and how the clinically available histone deacetylases 1 and 2 (HDAC1/2) inhibitor drug Romidepsin epigenetically modulates VCAM-1 expression to suppress atherosclerosis." (PMID 33859766, 2021). "We provide here evidence that redox-sensitive imaging probe RB700 entrapped into VCAM-1-targeted PEGylated Lp localize reliably and quantify directly the formation of ROS within the atheromatous plaque and in various organs in experimental atherosclerosis." (PMID 33763173, 2021). "In early atherosclerosis in particular, VCAM-1 is known to play a critical role." (PMID 33673124, 2021).
atherosclerosis (continued). "CyPA is known to promote atherosclerosis through stimulation of low-density lipoprotein uptake, decrease of endothelial nitric oxide synthase (eNOS) expression, increase of vascular cell adhesion molecule 1 (VCAM-1), and induction of tumor necrosis factor alpha (TNFα)." (PMID 34552938, 2021). "ECD is initiated by multiple inflammatory factors in atherosclerosis; when the endothelium is injured, inflammatory mediators, including vascular cell adhesion molecule-1 (VCAM-1), intercellular adhesion molecule-1 (ICAM-1), interleukin 6 (IL-6), and tumor necrosis factor α (TNF-α)are expressed." (PMID 34899318, 2021). "Increased expression of vascular cell adhesion molecule (VCAM)-1 on the activated arterial endothelial cell (EC) surface critically contributes to atherosclerosis which may in part be regulated by epigenetic mechanisms." (PMID 33859766, 2021). "Atherosclerosis is characterized by inflammation involving endothelial cell activation and secretion of adhesion molecules such as vascular cell adhesion molecule-1 (VCAM-1) and mobilization of monocytes to the arterial wall." (PMID 33498671, 2021). "The difference between the two is that ICAM-1 is higher than normal in all stages of atherosclerosis, while VCAM-1 only increases rapidly and significantly when the disease is initially formed, or when there is a sharp change in inflammation, such as vasospasm and plaque instability." (PMID 35071362, 2021). "Augmented induction of endothelial VCAM1 expression by circulating factor(s) may play a role in the development of atherosclerosis in diabetes." (PMID 34179515, 2021). "Activation for binding of leukocytes with VCAM1 relies on local microenvironmental factors including chemokine profile and has been shown to play a role in endothelial integrity and function in pathological states, such as atherosclerosis." (PMID 33971895, 2021). "This suggested that the LDL-oxLDL-LPC axis may regulate ICAM-1/VCAM-1 expression in the context of atherosclerosis." (PMID 34346841, 2021). "Despite several in vitro and in vivo reports on the anti-inflammatory effect of shear-sensitive miR-10a in ECs, the role of endothelial miR-10a/GATA6/VCAM-1 signaling during the progression of human atherosclerosis remains unclear in vivo." (PMID 34336268, 2021). "In addition, the accumulation of VCAM-1-targeted iron nanoparticles in atherosclerotic lesions highlighted the applicability of atherosclerosis imaging with MRI." (PMID 35071257, 2021). "Under high glucose conditions, vascular endothelial cells produce high levels of proinflammatory cytokines, such as TNF-α and IL-1β, ROS (reactive oxygen species) and high levels of VCAM-1 and E-selectin, which initiate atherosclerosis via adhesion of circulating leukocytes to the endothelium." (PMID 34445477, 2021). "Then, to enable the targeted delivery of RB700 at the sites of atheroma, peptides that specifically recognize VCAM-1, a molecule expressed by the dysfunctional endothelium in atherosclerosis, were conjugated on the surface of the Lp containing PEG-derivatized phospholipids." (PMID 33763173, 2021). "3-HAA has been demonstrated to be a compound with properties reducing the expression of the vascular cell adhesion molecule (VCAM)-1, which mediates the adhesion of immunological cells to the vascular endothelium and plays an important role in atherosclerosis development." (PMID 34199713, 2021). "During the genesis of atherosclerosis, inflammation induces endothelial cells to express adhesion molecules vascular cell adhesion protein 1 (VCAM-1), intercellular adhesion molecule 1 (ICAM-1), and E-selectins which leads to the adhesion of monocytes to endothelial cells." (PMID 33996157, 2021).
atherosclerosis (continued). "Humanin treatment also inhibits the high glucose-induced secretion of TNF-α and IL-1β and reduces the expression of VCAM-1 and E-selectin, thus preventing hyperglycaemia-induced attachment of the monocytes to the vascular cells, endothelial dysfunction and atherosclerosis progression." (PMID 34445477, 2021). "VCAM-1 can selectively adhere to mononuclear leukocytes and lymphocytes, mediates the recruitment of circulating monocytes and their adhesion and migration to vascular wall, and plays a vital role in the initiation of atherosclerosis." (PMID 35071362, 2021). "In addition, VEGF is closely related to vascular inflammation and VCAM‐1 released by vascular endothelium is deemed to an activator of atherosclerosis." (PMID 34114347, 2021). "Similarly, there is evidence that TGF-β played an anti-atherosclerosis role for its partial disruption of vascular cell adhesion molecule 1 (VCAM-1), and intercellular adhesion molecule 1 (ICAM-1) expression in mouse models of accelerated atherosclerosis." (PMID 33276745, 2020). "The mechanism of corylin’s protective and treatment effects on atherosclerosis progression may involve the inhibition of inflammation and VCAM-1 expression in VSMCs." (PMID 32218307, 2020). "As a major microbial metabolite of proanthocyanidin, 5-(3’,4’-dihydroxyphenyl-γ-valerolactone) prevents THP-1 monocyte-endothelial cell adhesion by downregulating expressions of vascular cell adhesion molecule-1 and monocyte chemotactic protein-1, which are biomarkers of atherosclerosis." (PMID 32013236, 2020). "Both ICAM‐1 and VCAM‐1 accelerate the development of various diseases such as atherosclerosis." (PMID 31993189, 2020). "Notably, as an adhesion molecule, vascular cell adhesion molecule-1 (VCAM-1) is reported to play critical role in the progression of atherosclerosis by mediating inflammatory response, and it has been considered as an effect target against atherosclerosis." (PMID 32314783, 2020). "Particularly, VCAM‐1 is one of the primary endothelial adhesion molecules that play a vital role in the aggregation of monocytes to the vascular endothelium, which is a crucial process during the development of atherosclerosis." (PMID 31993189, 2020). "The serum levels of soluble VCAM-1 appear to be correlated with the degree of atherosclerosis and may be used for diagnosing the early stages of the condition." (PMID 32942670, 2020). "However, microbubbles tend to remain close to the axial centre of blood vessels, which is a disadvantage for targeting atherosclerosis in larger vessels, and their bonding with VCAM-1 is influenced by shear stress forces." (PMID 33138124, 2020). "However, the antioxidant properties of selenium supplementation, was found to reduce both oxidative stress and VCAM-1 levels in healthy rats exposed to PM, which would be expected to influence the early stages of atherosclerosis." (PMID 31923583, 2020). "Moreover, VCAM-1 has a major role in the initiation of atherosclerosis and is present in early lesions." (PMID 33138124, 2020). "Cellular adhesion molecules (CAMs), such as intercellular adhesion molecule 1 (ICAM-1) and vascular cell adhesion molecule 1 (VCAM-1), contribute to the recruitment and migration of circulating monocytes into the vessel wall, leading to a vascular inflammatory response in atherosclerosis." (PMID 31623159, 2019). "Preclinical data has also suggested that canagliflozin may reduce infarct size as well as the progression of atherosclerosis, adhesion molecules, and markers of inflammation (i.e., vascular cell adhesion molecule-1 and monocyte chemotaxis protein-1)." (PMID 31138195, 2019). "In the progression of the atherosclerosis, endothelial-leukocyte adhesion molecules including vascular cell adhesion molecule-1 (VCAM-1) and E-selectin play a key role in the early adhesion of mononuclear leukocytes to arterial endothelium at sites of atheroma initiation." (PMID 30884801, 2019).
atherosclerosis (continued). "HU enhanced MCP‐1, ICAM‐1 and VCAM‐1 as shown in serum level and protein expression, suggesting that these three molecules are also involved in a HU‐driven atherosclerosis promoting effect that would exacerbate the pathogenesis of atherosclerosis." (PMID 30690853, 2019). "Endothelial activation, characterized by excessive cytokines (IL-6 and IL-8) production and adhesion molecules (ICAM-1 and VCAM-1) expression, is a crucial factor in the development of atherosclerosis and SCFA regulated endothelial activation in different ways." (PMID 29615908, 2018). "Galectin-3 handling and VCAM-1-driven pathways overlap in leukocyte trafficking and atherosclerosis, suggesting galectin-3 and VCAM-1 may share common pathogenesis in CV mortality." (PMID 30249969, 2018). "Excessive expression of ICAM-1 and VCAM-1 is regarded as an early event of atherosclerosis." (PMID 29615908, 2018). "VCAM-1 expressed in atherosclerosis has been the main target of research." (PMID 29853809, 2018). "This shows the importance of VCAM-1 in cell adhesion and the development of atherosclerosis." (PMID 29875665, 2018). "Studies have shown that VCAM-1 plays a dominant role in the initiation of atherosclerosis." (PMID 29423081, 2018). "Background and Aim: Previously, we found that short chain fatty acids (SCFA) inhibit LPS or TNFα-induced endothelial inflammatory responses and excessive vascular cell adhesion molecule-1 (VCAM-1) expression, two important steps in the development of atherosclerosis." (PMID 29875665, 2018). "Moreover, signals from targeted microbubbles increased from 8wks to 32wks age (P<0.05 for trend) in ApoE-/- mice, indicating the upregulation of VCAM-1 with the progression of atherosclerosis." (PMID 28982198, 2017). "Also, dihydrotestosterone increases smooth muscle proliferation and expression of vascular cell adhesion molecule 1, which enhances monocyte activation in the endothelium and promotes atherosclerosis." (PMID 28770092, 2017). "CD44 and VCAM1 were increased in an atherosclerosis mouse-model too." (PMID 28323859, 2017). "Furthermore, decreased VCAM-1 expression in experimental atherosclerosis appears after treatment with either HMG-CoA reductase inhibitors or angiotensin receptor blockers." (PMID 28044245, 2017). "In our study, VCAM-1 expressed on the endothelium was chosen as the inflammatory target for molecular imaging because of its function to recruit monocytes and lymphocytes to the arterial intima in the early stage of atherosclerosis." (PMID 28982198, 2017). "The use of soluble VCAM-1 over membrane-bound VCAM-1 could be a limitation because it is the membrane-bound VCAM-1 that binds directly to leukocytes in the progression of atherosclerosis." (PMID 26843586, 2016). "The present results showed that there was a significant correlation between the aortic VCAM-1 expression and the SYNTAX score, suggesting that VCAM-1 may participate in the occurrence and development of atherosclerosis." (PMID 26622332, 2015). "Interestingly, this supports the positive association observed between arsenic exposure and increased human soluble VCAM-1 concentration in the plasma, which is known to increase with endothelium activation in atherosclerosis." (PMID 26332580, 2015). "Cellular adhesion molecules, including ICAM-1 and VCAM-1, are over-expressed by the vascular endothelium in the initial process of atherosclerosis, which may lead to upregulation of endothelium cell adhesion and atherosclerotic lesions." (PMID 25933220, 2015). "Importantly we demonstrated that among several commonly used risk factors and markers of atherosclerosis, carotid eVCAM-1 best predicted the severity of CAD, particularly in the LAD, supporting a clinical use for carotid VCAM-1 in the diagnosis of CAD." (PMID 26702331, 2015).
atherosclerosis (continued). "Thus, we focused our investigations on VCAM-1, and found that atherogenic concentrations of arsenic induced vascular endothelial VCAM-1 expression at lesion-prone sites in apoE-/- mice model of atherosclerosis." (PMID 26332580, 2015). "Meanwhile, the expressions of IL-6, TNF-α, MCP-1 and VCAM-1 were up-regulated in apoE-/- mice treated with salusin-β, indicating that salusin-β could aggravate the progression of atherosclerosis via up-regulation of inflammatory molecules." (PMID 24621517, 2014). "In fact, previous studies have reported that some components of the MD such as EVOO or nuts may down-regulate inflammatory markers related to atherosclerosis such as VCAM-1, ICAM-1, E- and P-Selectin, CRP and IL-6." (PMID 24925270, 2014). "Moreover, oxidized LDL stimulates macrophages and vascular endothelial cells to express inflammatory factors, including VCAM-1 and monocyte chemoattractant protein-1, which promote atherosclerosis." (PMID 24722330, 2014). "Meanwhile, BPA exposure affected the functions of endothelial cells, inducing the up-regulation of surface adhesion molecules (VCAM-1), which can increase permeability, enhance leukocyte adhesion, and promote monocyte emigration, contributing to the development of atherosclerosis." (PMID 25333893, 2014). "Recent data have strongly suggested that VCAM-1 may play an important role in the pathogenesis of atherosclerosis because VCAM-1 function in leukocyte adhesion and transmigration is crucial and its expression is induced early in nascent atheroma plaques." (PMID 24499567, 2013). "Losartan may be acting on inhibiting protein of nuclear factor κB and lead MCP-1, VCAM-1, E-selection in adhesion process to reduce, inhibiting the inflammatory response in occurrence of atherosclerosis." (PMID 25478508, 2013). "We hypothesized that molecular imaging of vascular cell adhesion molecule-1 (VCAM-1) with contrast enhanced ultrasound (CEU) could assess treatment effects on endothelial phenotype in early atherosclerosis." (PMID 23554922, 2013). "Indeed, VCAM-1 plays a more important role than intracellular adhesion molecule (ICAM-1) in the early progression of atherosclerosis." (PMID 23573162, 2013). "VCAM-1 is expressed on endothelial cells during the earliest stages of atherosclerosis, and has been shown to be an ideal target for ultrasound molecular imaging of vascular inflammation in both early and established atherosclerosis." (PMID 23554922, 2013). "VCAM1 is a cell adhesion molecule that mediates adhesion of leukocytes to vascular endothelium, leading to vascular inflammation, one of the early stages in atherosclerosis development." (PMID 23536757, 2013). "Finally, previous studies have suggested that upregulation of cell adhesion molecules expression, such as ICAM -1 and VCAM-1, play an important role in atherosclerosis development." (PMID 23469284, 2013). "Vascular cell adhesion gene (VCAM1), which may play a role in atherosclerosis and rheumatoid arthritis, showed a 30-fold increase in expression in DD." (PMID 23554969, 2013). "In the present study, we therefore investigated whether in vivo ultrasound molecular imaging of the expression of VCAM-1 could be used to assess the effects of pharmacologic therapy on vascular endothelial phenotype in a mouse model of early atherosclerosis." (PMID 23554922, 2013). "Restenosis after carotid surgical mechanical de-endothelialization (CSMDE) is reduced, if VCAM-1 expression is inhibited by siRNA, thus siRNA against VCAM-1 could be a therapeutic option against atherosclerosis as well." (PMID 24276320, 2013). "The inflammation process in large vessels involves the up-regulation of vascular adhesion molecules such as endothelial cell selectin (E-selectin), intercellular cell adhesion molecule-1 (ICAM-1) and vascular cell adhesion molecule-1 (VCAM-1) which are also known as the markers of atherosclerosis." (PMID 24129228, 2013).